L1CAM-AS1 (L1CAM antisense RNA 1)
Synonyms: LCA10; LCAP
Gene: Long non-coding RNA gene on chromosome X (153,879,166 to 153,888,990, forward strand). Ensembl gene ENSG00000273769.
Diseases named in the same sentence as L1CAM-AS1 in open-access papers:
L1CAM-AS1 is named in the same sentence as 1 disease in open-access papers, as found by Europe PMC text mining. Sharing a sentence is not in itself a finding about the gene and the disease.
L1CAM-AS1 shares sentences with these, for which no sentence is quoted: liver steatosis (1 paper).